MALAT1 (metastasis associated lung adenocarcinoma transcript 1)
Diseases named in the same sentence as MALAT1 in open-access papers (continued):
Sharing a sentence is not in itself a finding about the gene and the disease.
cancer (continued). "MALAT1 (Metastasis-associated lung adenocarcinoma transcript 1) expression is associated with the tumor development, invasion, metastasis, and outcome in different types of cancer." (PMID 32760219, 2020). "To improve our understanding of the processes, we performed a comparison of previously published datasets from AMT and MAT experiments, which identified metastasis-associated lung adenocarcinoma transcript 1 (MALAT1) to be involved in cancer cell invasion plasticity." (PMID 32369931, 2020). "Polymorphisms in MALAT1 have been demonstrated to play critical roles in cancer." (PMID 31880028, 2020). "Moreover, MALAT1 SNPs modulated the risk of cancer by possibly affecting function or expression levels." (PMID 32238151, 2020). "Furthermore, MALAT1, an abundant lncRNA that has been implicated in cancer metastasis, was slightly upregulated in C-LM." (PMID 33375322, 2020). "In addition to providing protein/RNA-binding structural information, this study reveals that the structure of lncRNA MALAT1 can be perturbed by RNA modifications, mutations in cancer, and single-nucleotide polymorphisms." (PMID 32429086, 2020). "Metastasis associated lung adenocarcinoma transcript 1 (MALAT1), a tumor-promoting lncRNA in many cancers has been shown to stimulate repair of ischemic wounds by promoting migration of human dermal fibroblasts through hypoxia-inducible factor-1α (HIF-1α) signaling." (PMID 32462404, 2020). "To further investigate the relationship between MALAT1 and IAPs in HCC, we conducted a comprehensive search in the public database Starbase and miRcode, and four miRNAs (miR‐22‐3p, miR‐455‐5p, miR‐338‐3p and miR‐101‐3p) were identified to be linked with MALAT1 in cancer." (PMID 33135336, 2020). "LncRNAs have recently been associated with several cancer models and also UM carcinogenesis; in particular, a recent study showed that the oncogenic function of MALAT1 (metastasis associated lung adenocarcinoma transcript 1) in UM is performed through the regulation of an RNA-based network." (PMID 33371395, 2020). "In such cases, MALAT1 might compensate for ‘loss of function’ cancer cell mutations that prevent adaptation to new niches or derepress ‘gain of function’ mutations that promote spread by reducing cell attachment." (PMID 32742689, 2020). "Moreover, MALAT1 is one of the first identified cancer-associated lncRNAs; it is upregulated in several cancers, and its deregulation is considered a prognostic biomarker for particularly aggressive tumors." (PMID 33193626, 2020). "MALAT1 is a highly-conserved noncoding RNA gene transcribed from the human 11q13 locus which has been shown to exhibit copy number changes, translocations, or mutations in several cancer types." (PMID 32503170, 2020). "In addition, several reports have indicated that MALAT1 is expressed in CSCs of various cancers and has been linked to EMT, a CSC feature." (PMID 32760219, 2020). "According to lnc2Cancer, the most studied cancer-associated lncRNAs are MALAT1, H19, HOX antisense intergenic RNA (HOTAIR), maternally expressed 3 (MEG3), taurine upregulated 1 (TUG1), antisense non-coding RNA in the INK4 locus (ANRIL) and nuclear-enriched abundant transcript 1 (NEAT1)." (PMID 32340118, 2020). "We highlighted two cancer-associated mutations that could affect the binding of miR-23 to MALAT1, which act as a competitive endogenous RNA for miR-23 and could potentiate cancer." (PMID 31717552, 2019). "A total of 655 mutations in MALAT1 have been reported for 26 types of cancer." (PMID 31717552, 2019). "Aberrant MALAT1 expression is implicated in cancer progression and in metastasis." (PMID 31717552, 2019). "In addition, a comprehensive review published recently describes MALAT1 as highly associated with human cancers and presents a list of 28 genes that regulate the expression of MALAT1 during transcriptional and posttranscriptional processing." (PMID 30512195, 2019).
cancer (continued). "Integrating our secondary structural model of MALAT1 with protein- and RNA-binding sites, RNA modifications, cancer-associated mutations, and SNPs unexpectedly revealed new mechanisms by which MALAT1 may function in cancer." (PMID 31717552, 2019). "Aberrant expression of MALAT1 was significantly associated with tumor invasion and metastasis, indicating this lncRNA could be a prognostic marker for cancers." (PMID 31788131, 2019). "Malat1 is known to interact with many miRNAs implicated in cancer." (PMID 31616462, 2019). "The MALAT1 gene is associated with cancer metastasis, cell migration, and cell cycle regulation." (PMID 31249598, 2019). "Accordingly, the alteration of MALAT1 splicing by m6A “reader” might associate with cancer progression." (PMID 29374143, 2018). "LncRNAs MALAT1 is associated with RA and involved in the development and metastasis of cancer." (PMID 30018955, 2018). "In this review, we summarize the emerging insights on lncRNA expression and functional role in cancer, focusing on the evolutionary conserved and abundantly expressed metastasis-associated lung adenocarcinoma transcript 1 (MALAT1) that currently represents the best characterized lncRNA." (PMID 29739426, 2018). "These associations suggest that targeting MALAT1 may have important clinical implications because it selectively affects cancer cells or residual cancer cells." (PMID 29156758, 2017). "However, given the association of this lncRNA in many different kinds of cancer, the specificity of MALAT1 as a biomarker for HCC will need to be addressed." (PMID 30159431, 2017). "In summary, our findings provide evidence that elevated MALAT-1 appeared to be a potential diagnostic marker for patients with cancer and could be rated as an auxiliary marker to aid in cancer diagnosis." (PMID 29254244, 2017). "The overexpression of MALAT1 is generally associated with poor prognosis in patients with various types of cancer, even though the mechanisms underlying this relationship remain unclear." (PMID 29165379, 2017). "The role of MALAT1 in tumorigenesis has been deeply investigated; its overexpression has been associated with the promotion of malignancy, while its knockdown is linked to the inhibition of cell proliferation and invasion in different cancer types." (PMID 29165379, 2017). "Besides, our gain and loss function assay showed that MALAT1 suppressed miR-203 expression, a miRNA reported to play important roles during cancer progression and chemoresistance." (PMID 28187000, 2017). "The diagnostic feature of MALAT-1 in cancers has been documented by many single studies." (PMID 29254244, 2017). "The MALAT1 long noncoding RNA is strongly linked to cancer progression." (PMID 29632545, 2017). "In addition, recent reports have indicated that MALAT1 expression is significantly associated with poor prognosis in various malignant tumors." (PMID 28412742, 2017). "We therefore determined whether overexpression of MALAT1 influences the alternative splicing of key cancer-associated genes in MD-MBA-435s cells." (PMID 27250026, 2016). "MALAT1 seems the most frequently lncRNA mutated in human cancers." (PMID 27172249, 2016). "Among these, we found MALAT1, the abundant nuclear-retained lncRNA found overexpressed in several cancers associated with high proliferation and metastasis, although the underlying mechanism(s) behind this deregulation and its significance in tumorigenesis is still poorly understood." (PMID 26895470, 2016). "MALAT1 was one of the first lncRNAs to be implicated in cancer and a series of studies have established its potential importance as a biomarker and potential therapeutic target for cancer metastasis." (PMID 27144026, 2016). "MALAT1 is associated with tumor metastasis and is overexpressed in several human carcinomas." (PMID 26578588, 2016).
cancer (continued). "In an RNA-seq analysis of 14 paired-tumor and adjacent benign prostate tissues, metastasis associated with lung adenocarcinoma transcript 1 (MALAT-1) was found to be overexpressed in cancer samples, and its expression was correlated with a high Gleason score, tumor stage, and CRPC tumors." (PMID 26690121, 2015). "Consistent with that result, our functional prediction for Malat1 is closely associated with terms such as ‘Pediatric cancer markers’, ‘Establishment of RNA localization’, ‘RNA transport’, ‘Cell division’, ‘Mitotic cell cycle’, and ‘Cell cycle phase’, among others." (PMID 26683846, 2015). "Notably, tissue-specific functions and regulation have also been reported for another cancer-associated lncRNA, MALAT1." (PMID 25994132, 2015). "In addition, the long noncoding RNA MALAT1 (metastasis-associated lung adenocarcinoma transcript 1), is frequent misregulation and as a predictive marker for a variety of human cancers of the colon, breast and prostate." (PMID 24595048, 2014). "In addition to ZEB2-AS1, MALAT1 is another nuclear-retained lncRNA which has been directly linked to cancer metastasis and interestingly also plays a role in alternative splicing." (PMID 24346158, 2014). "However, MALAT1 was implicated to play an oncogenic role and upregulation of MALAT1 was observed in several other cancers, e.g. of the breast and prostate." (PMID 24313945, 2013). "In this review, we focus on some well-characterized lncRNAs associated with the progression of cancer, namely metastasis-associated lung adenocarcinoma transcript 1 (MALAT1), HOX antisense intergenic RNA (HOTAIR), and antisense non-coding RNA in the INK4 locus (ANRIL)." (PMID 23109937, 2012). "The elucidation of the intricate mechanisms through which MALAT-1 is implicated in the etiology of cancer and its resistance to chemotherapy will facilitate the development of novel therapeutic interventions and personalized treatment strategies in the fight against cancer." (PMID 38511067, 2024). "However, to improve diagnostic sensitivity and accuracy, MALAT1 might be used in clinical diagnosis as a complementary biomarker for hematic cancer detection." (PMID 36831169, 2023). "Moreover, MALAT1 is a widely studied lncRNA originally reported to be associated with metastasis in the early stage of non-small cell lung cancer and is subsequently found to be involved in a variety of cancers." (PMID 35534592, 2022). "Furthermore, Tiansheng and colleagues noted that a high expression of lncRNA Metastasis Associated Lung Adenocarcinoma Transcript 1 (MALAT1) was associated in NSCLC cancers with a lower expression of miR-202 and with large tumor size, advanced cancer, and tumor metastasis." (PMID 35682549, 2022). "Single-nucleotide polymorphisms (SNPs) of MALAT1 could alter the oncogenesis in various cancers." (PMID 34574033, 2021). "Metastasis-associated lung adenocarcinoma transcript 1 (MALAT1), a 8000 nt-long single-exon noncoding transcript highly expressed in nucleus, is upregulated in many solid cancers and regulates alternative splicing or transcription to promote cancer progression, metastasis, and recurrence." (PMID 30683916, 2019). "Furthermore, we mapped known protein-binding sites, intermolecular RNA interaction sites for miRNAs and other RNAs, RNA modifications, somatic cancer-associated mutations, and single-nucleotide polymorphisms (SNPs) to relate structure to prior functional observations of MALAT1." (PMID 31717552, 2019). "However, in this pathophysiological condition, also the cancer-associated lncRNA MALAT1 has been proposed to be of potential relevance, being highly expressed in the peripheral blood of infarcted mice as a possible consequence of endogenous activation of the hypoxia pathway." (PMID 31191327, 2019).
cancer (continued). "Disruption of PK7 in cancer cells, whether it is caused by m6A5044, protein-binding partners, or RNA-binding partners, would expose binding sites for miR-101, miR-217, and miR-383, allowing MALAT1 to sponge these miRNAs." (PMID 31717552, 2019). "Somatic mutations associated with cancer or other diseases may also alter the structure of MALAT1." (PMID 31717552, 2019). "In addition, the MTFs uniformly expressed very high levels of MALAT1, a long non-coding RNA transcript known to be involved in control of metastasis, as well as additional long non-coding transcripts implicated in cancer progression." (PMID 28957348, 2017). "In addition, MALAT1 is associated with the chemo-resistance of many cancers." (PMID 29212230, 2017). "However, the mechanisms underlying aberrant expression of MALAT1 in cancers remain elusive." (PMID 27777857, 2016). "Additionally, upregulation of MALAT1 in the ‘Bad’ samples may suggest this gene to be further explored as it is upregulated in many other tumours too and associated with cancer metastasis and recurrence." (PMID 22925330, 2012). "This ceRNA mechanism is similarly observed in other cancers, with MALAT1 modulating tumor behavior through interactions with various miRNAs." (PMID 41584724, 2026). "A significant body of recent studies has revealed that MALAT1 is raised in various cancer types, including BC." (PMID 41459628, 2026). "Nuclear MALAT1 significantly influences the processes above when cancer cells proliferate, invade, and migrate." (PMID 41459628, 2026). "It was observed that RSV at increasing concentrations (up to 5 μM) decreased the expression of MALAT1 (lncRNA involved in cancer progression)." (PMID 41596402, 2026). "Scientists have discovered that long ncRNAs MALAT1 and HOTAIR demonstrate substantial value for liquid biopsy exams as cancer diagnostic and prognostic indicators across numerous cancer types." (PMID 40959208, 2025). "Our data reinforce these findings, suggesting that MALAT1 is actively involved in HPV‐induced cancer progression." (PMID 41261348, 2025). "Specifically, we analyze the functions of lncRNAs, including HOTAIR and MALAT1, in key processes such as apoptosis, DNA damage response and repair, cancer stem cell regulation, and drug metabolism." (PMID 41276852, 2025). "lncRNAs regulate drug transporters in cancer cells, such as MALAT1 and ANRIL which control the expression of Multidrug resistance protein 1 (MRP1) and Multidrug resistance gene 1 (MDR1)." (PMID 40352931, 2025). "Its highly conserved nature and multifaceted role in cancer biology have made MALAT1 a focal point for research into mechanisms of metastasis and therapeutic resistance." (PMID 40674376, 2025). "MALAT1 is one of the most extensively studied lncRNAs in humandiseases and is widely described to be involved in cancer development." (PMID 41123190, 2025). "The upregulation of lncRNA with oncogenic potential such as HOTAIR, MALAT1, PCAT1, H19 have been reported in various cancer types and have been associated with various processes contributing to cancer development." (PMID 39912983, 2025). "For example, MALAT1 is overexpressed in several cancers and promotes tumor growth and metastasis by regulating gene expression and alternative splicing." (PMID 40282307, 2025). "These genes, including immunoglobulin-related genes, Transgelin (TAGLN), Keratin 19 (KRT19), Metastasis-associated lung adenocarcinoma transcript 1 (MALAT1), and superoxide dismutase (SOD2), play a role in the EMT process in various cancers." (PMID 41035074, 2025). "Extensive research has been conducted on the role of METTL16 in regulating cancer progression through m6A modification of target genes, including U6 snRNA, MALAT1, XIST, and RAB11B‐AS1, and mRNA (MAT2A, VPS33B, FGFR4, and GPX4)." (PMID 40095756, 2025).
cancer (continued). "The in vitro experiments provide further mechanistic validation, illustrating that MALAT1 expression is markedly higher in MCF7 cells compared to normal breast epithelial MCF10 cells, suggesting a cancer‐specific role for MALAT1 in driving oncogenic processes." (PMID 41031251, 2025). "For instance, MALAT1 was involved in 195 synergistic pairs shared across two or more cancers, while CRNDE was involved in 148 such pairs." (PMID 40728857, 2025). "Key lncRNAs associated with BC include H19, which promotes cancer cell proliferation, and MALAT1, which facilitates distant metastasis of cancer cells." (PMID 40313963, 2025). "Recently, lncRNA MALAT1 has emerged as a key regulator of cancer cell biology, influencing diverse processes including proliferation, apoptosis, invasion, migration, and EMT." (PMID 39319867, 2025). "One of the most studied oncogenic lncRNAs across cancers, MALAT1 (Metastasis-Associated Lung Adenocarcinoma Transcript 1), was found to be significantly elevated in HNSCC patients’ plasma exosomes compared to those of healthy controls." (PMID 40941749, 2025). "Recent research also shows that MALAT-1 plays a role in changing how cancer cells use energy, improving mitochondrial function, and helping cells to survive upon stress and chemotherapy." (PMID 41029313, 2025). "Studies have shown that XIST and MALAT1 exhibit opposing expression patterns in cancer tissues and TNBC cells." (PMID 40223929, 2025). "SOX2, PIWI proteins, and MALAT1 were significantly elevated in cancer patients versus controls (p < 0.001), with qRT-PCR and ELISA results strongly correlated." (PMID 40674376, 2025). "Researchers have discovered that MALAT1 can inhibit the distant metastasis of cancer cells in triple-negative BC patients by regulating HIF-1α." (PMID 40313963, 2025). "Genistein inhibits the expression of oncogenic lncRNAs such as HOTAIR and MALAT1 in various cancer cell lines." (PMID 39825964, 2025). "Malat1 is known to promote cellular proliferation and is considered to be a curative target for cancer and metabolic syndromes such as Type 2 diabetes." (PMID 41256287, 2025). "MALAT1 showed consistent AUC values across all cancers (0.82–0.88), and PIWI proteins ranged from 0.81–0.85." (PMID 40674376, 2025). "LncRNAs such as NORAD and MALAT1 play significant roles in the progression of cancer to bone metastasis." (PMID 40872531, 2025). "Transcriptomic analysis further demonstrates that MALAT1 regulates a variety of cancer-related signaling pathways, underscoring its pivotal role as an oncogenic factor in NSCLC." (PMID 40723840, 2025). "While the oncogenic role of MALAT1 has been previously documented in various cancers, the specific involvement of MAP2K1 in the MALAT1-mediated regulatory network within HSCC has not been reported until now." (PMID 39319867, 2025). "As an example of this, the lncRNA MALAT1 has been studied as a potential therapeutic target, and in multiple tumor types; MALAT1 inhibition has demonstrated anti-cancer effects, although these strategies are yet to become routine clinical practice." (PMID 41154428, 2025). "MALAT1, which spans the Alpha locus at 11q13.1, is overexpressed in multiple cancers including early‐stage NSCLC." (PMID 40783798, 2025). "In the intergenic category, we found two well-known lncRNAs; MALAT1, traditionally studied for its role in cancer and Cyrano, previously shown experimentally to be inherited in zebrafish by our group." (PMID 40677736, 2025). "The high levels of MALAT1 expression serve as an important biomarker for liquid biopsy because they signal poor outcomes and metastasis development during cancer detection and monitoring." (PMID 40959208, 2025).